BDNF (brain derived neurotrophic factor)
Diseases named in the same sentence as BDNF in open-access papers (continued):
Sharing a sentence is not in itself a finding about the gene and the disease.
Anxiety (continued). "While it is not clear how each of these growth factors uniquely contributes to modulating depressive and anxiety-like behaviors, unlike BDNF and VEGF, FGF2 is largely produced by astroglial cells, and the effects of FGF2 on neuroplasticity are typically mediated through astroglial cells." (PMID 30273396, 2018). "Neither LPS nor propentofylline has influenced the anxiety and BDNF levels of rats." (PMID 28056040, 2017). "The normalized change in BDNF levels was inversely correlated with BSI-18 anxiety scores at both the pre-retreat (r = 0.40, p < 0.05) and post-retreat (r = 0.52, p < 0.005) such that those with greater anxiety scores tended to exhibit smaller pre- to post-retreat increases in plasma BDNF levels." (PMID 28694775, 2017). "The evidence linking BDNF with anxiety-like behaviors in animal models is not as abundant or clear." (PMID 25932008, 2015). "In particular, neuroplastic changes, including neurogenesis and increases in BDNF, may be required for DBS improvements in behaviours with predominant anxiety-like and anhedonic-like components but are unlikely responsible for broader antidepressant-like responses to this therapy." (PMID 26529427, 2015). "LPS also decreased BDNF expression but did not influence anxiety parameters." (PMID 25775356, 2015). "To date, there has been no published meta-analysis of BDNF protein levels in anxiety." (PMID 23908608, 2013). "By blocking neurogenesis and thereby altering anxiety without any changes in BDNF levels, we could demonstrate that BDNF failed to correlate with anxiety." (PMID 20862278, 2010). "Second, the study did not perform astrocyte-specific BDNF overexpression experiments, which would provide critical complementary evidence to determine whether astrocytic BDNF directly mitigates stress-induced anxiety-like behaviors." (PMID 40777598, 2025). "In this work we studied the influence of transient expression (P3–P8) elevation of pro-, mature and mutant forms of BDNF that could not be processed with cellular convertases in the neonatal medial prefrontal cortex (mPFC) on anxiety and depressive-like behavior in adolescents." (PMID 39619203, 2024). "BDNF conditional mutant mice absent of central BDNF were found to be hyperactive after exposure to stress, and had higher level of anxiety when evaluated in the light/dark exploration test, indicating serotonergic dysfunction might be involved in this behavioral abnormality in mutant mice." (PMID 35815047, 2022). "Similar to individuals who have recovered from AN and continue to show higher levels of anxiety, ABA induction increases anxiety-like behavior also after a recovery period, an effect that might be driven by the herein shown persistent changes in the BDNF system in the Amy." (PMID 36570702, 2022). "A recent comprehensive study revealed that adult BDNF rats with the Met/Met genotype have a specific impairment in conditioned fear memory compared to Val/Met heterozygotes and Val/Val controls that does not extend to differences in fear learning, extinction, or anxiety-like behaviour." (PMID 35625351, 2022). "Therefore, modulation of the BDNF-ERK signaling pathway may increase fear-related freezing behavior and anxiety-like symptoms by enhancing hippocampal-dependent memory and promoting memory-related synaptic changes, as seen in long-term potentiation, for example." (PMID 35722162, 2022). "The issue with non-selective activation of BDNF/TrkB signaling is apparent from chronic stress studies demonstrating that enhanced BDNF/TrkB signaling in the amygdala leads to maladaptive plasticity resulting in overactivation of this brain region and exacerbated anxiety and fear responses." (PMID 34671279, 2021). "In addition, given that BDNF did not decrease escape behavior in the forced swim test, indicative for anxiety-like behavior, it is still unclear which circuits might be involved in the forced swim test escape-behavior response." (PMID 34068707, 2021).
Anxiety (continued). "While anxiety/fear indices were all very strongly correlated, functional connectivity between right amygdala and right orbitofrontal cortex, and right amygdala activation and serum BDNF concentration were not correlated with each other, and not correlated with LSAS." (PMID 33408651, 2020). "In addition, BDNF is known to protect neuronal cells against oxidative stress.Although LBP decreases anxiety levels by changing antioxidant biomarkers, it is unknown whether or not the anxiolytic effects of LBP on ovariectomized rats are caused by increasing hippocampal SERs." (PMID 33110362, 2020). "Moreover, sedentary individuals are more likely to have lower brain-derived neurotrophic factor (BDNF) concentration—a biological marker for suicidal behaviors—which may influence neural homeostasis, increased anxiety and aggression levels, and self-injurious actions." (PMID 33146359, 2020). "Anxiety-like behavior was the only domain where the occurrence of the symptoms could be compared between the studies which had found or had not found the decreased BDNF expression." (PMID 28620285, 2017). "Co-morbid CS in WD mice induced anxiety-like behavior and anhedonia, coupled with WD-related reductions in FC GABA and HPC BDNF not evident in un-stressed mice." (PMID 42043687, 2026). "While LEV administration improves BDNF levels and spatial navigation, the current study demonstrates that LEV monotherapy alone does not effectively improve spatial memory and anxiety‐like behaviors induced by hypothyroidism." (PMID 38988101, 2024). "Comorbid anxiety and personality disorders did not modulate the sleep quality of the patients, CAR, or BDNF levels." (PMID 32410966, 2020). "Moreover, correlations between anxiety symptoms registered in HARS and BDNF levels were not statistically significant among the normal (r = 0.34, t = 1.0, df = 8, p = 0.3), moderate (ρs = 0.17, p = 0.7), and severe groups (r = 0.4, t = 1.3, df = 10, p = 0.1)." (PMID 40943216, 2025). "The relevance of this approach is illustrated by a strong negative correlation between the amount of brain-derived neurotrophic factor (BDNF) in the hippocampus and the extent of anxiety-related behavior in the light/dark preference test, as reported by Yamamori and coauthors." (PMID 35563271, 2022). "In contrast, female PRS rats displayed reduced anxiety in the EPM, improved learning in the Morris water maze, an increase in the activity of mGlu1/5 receptors in the ventral and dorsal hippocampus, and no changes in hippocampal neurogenesis or BDNF levels." (PMID 18478112, 2008). "In this study besides BDNF, we did not investigated the other members of the neurotrophin family which also includes Nerve Growth Factor (NGF), Neurotrophin-3 (NT-3) and Neurotrophin-4/5 (NT-4/5) because the available data indicate that they are not useful as biomarkers of anxiety." (PMID 26539329, 2015).
Alzheimer disease (703 papers, 2008 to 2026). A progressive, neurodegenerative disease characterized by loss of function and death of nerve cells in several areas of the brain leading to loss of cognitive function such as memory and language. "Beyond its role in Alzheimer's disease, the BDNF gene and its encoded protein have been implicated in numerous other neurological and cardiovascular diseases." (PMID 41476008, 2026). "Ultimately, this work provides a compelling argument for BDNF-based therapies as a promising avenue for mitigating the cognitive decline associated with Alzheimer’s disease, signaling a hopeful direction for future research and clinical trials." (PMID 40380033, 2025). "Other neuropathologies linked to decreased BDNF levels and signaling are chronic and neuropathic pain, brain cancer, and neurodegenerative disorders, such as Alzheimer’s disease, Parkinson’s disease, and Huntington’s disease." (PMID 40710529, 2025). "Reduced levels of BDNF have been consistently associated with cognitive dysfunction across various neurological and psychiatric conditions, including depression, Alzheimer’s disease, and aging-related decline." (PMID 41155372, 2025). "Physical activity promotes an increased release of brain-derived neurotrophic factor (BDNF), which is associated with delayed cognitive decline and the prevention of the accumulation of a substance related to the development of Alzheimer’s disease." (PMID 41283454, 2025). "The combination of BDNF with tau and amyloid proteins in some studies has greatly heightened the accuracy of very early diagnostic approaches in respect to Alzheimer’s disease." (PMID 40362507, 2025). "Multiple neurodegenerative conditions, including Alzheimer's disease, Parkinson's disease, Huntington's disease, schizophrenia, and manic-depressive illness, are linked to a drop in BDNF activity." (PMID 37287291, 2024). "In recent years, compelling evidence has suggested neurogenesis impairment in Alzheimer’s disease to be linked to decreased levels of the BDNF in the hippocampus and the cortex." (PMID 38971770, 2024). "BDNF, along with its receptors, is implicated in the pathophysiology of neurodegenerative disorders such as Alzheimer's disease, amyotrophic lateral sclerosis, and Rett syndrome, positioning it as a potential therapeutic target." (PMID 38654189, 2024). "Declining hippocampal brain-derived neurotrophic factor (BDNF) has been implicated in the pathogenesis of Alzheimer’s disease (AD)." (PMID 38164567, 2024). "Decline in BDNF levels in the hippocampus of Alzheimer's disease patients was strongly associated with disease progression." (PMID 39285941, 2024). "Downregulation of BDNF transcription was observed in human neuroblastoma cells after exposure to oligomeric amyloid beta, one of the risk factors in the pathogenesis of Alzheimer’s disease." (PMID 38397748, 2024). "This can be considered an important finding for the treatment of neurodegenerative diseases related to BDNF deficiency, especially Alzheimer’s disease." (PMID 39594453, 2024). "BDNF has been linked to the etiology of Alzheimer’s disease, and its expression is reduced in the hippocampus and several cortical regions of Alzheimer’s patients." (PMID 37966574, 2024). "For example, BDNF can promote the growth and differentiation of neurons and enhance synaptic plasticity, and dysfunction in BDNF synthesis is an important risk factor for Alzheimer's disease or age‐related cognitive impairment." (PMID 38140846, 2024). "At the same time, the introduction of exosomes themselves into Alzheimer’s disease models led to an improvement in cognitive functions, which was associated with an increase in BDNF levels in the brain and a decrease in oxidative stress." (PMID 39596443, 2024). "In contrast, decreased levels of brain-derived neurotrophic factor are associated with poor memory function, neurodegeneration, and cognitive impairments associated with Alzheimer’s disease." (PMID 39451988, 2024).
Alzheimer disease (continued). "Deficiency of BDNF level is responsible for neurological disorders, like Alzheimer’s disease, vascular dementia, brain trauma, and stroke." (PMID 38333757, 2024). "Decreased BDNF expression has been associated with a range of neurological disorders, including schizophrenia, Alzheimer’s disease, and ASD." (PMID 39469188, 2024). "Some studies suggest that BDNF levels are linked to the occurrence of neurodegenerative disorders such as Alzheimer’s Disease (AD), Frontotemporal Dementia (FTD), Lewy Body Dementia (LBD), and Vascular Dementia (VAD)." (PMID 39876995, 2024). "miR-206 has been identified to modulate BDNF in the hippocampus of a learning-deficient mouse model and an Alzheimer's disease (AD) animal model." (PMID 38334898, 2024). "Hippocampal BDNF has been implicated in Alzheimer’s disease (AD) because hippocampal levels in AD patients and AD animal models are often downregulated, suggesting that reduced BDNF contributes to AD." (PMID 38164567, 2024). "BDNF gene polymorphism is associated with neurodegenerative diseases, with the rs6265 (Val66Met) polymorphism linked to the risk of Alzheimer’s Disease (AD) and related to cognitive function." (PMID 39876995, 2024). "Because increased BDNF is essential to neurogenesis and brain health, the downregulation of BDNF is a risk factor for various neuropsychiatric diseases including Alzheimer’s disease and stroke as well as various metabolic disorders." (PMID 37965360, 2023). "Dysfunctions in the BDNF pathway have been linked to Alzheimer’s disease, schizophrenia, Huntington’s disease, and Rett syndrome." (PMID 37958943, 2023). "Dysregulated BDNF-TrkB signaling is reported to be associated with Alzheimer’s disease and other neurodegenerative disorders." (PMID 39872114, 2023). "The potential linkages between neurodegenerative conditions such as Alzheimer's disease and the Val66Met polymorphism in BDNF are crucial for the survival and maintenance of neurons." (PMID 38015338, 2023). "At the same time, the reduction of BDNF enforces the susceptibility to Alzheimer’s disease and other age-related neurodegenerative disorders." (PMID 36334250, 2023). "A recent study has shown that reduced serum BDNF is associated with Alzheimer’s disease (AD) pathology and can be used as a biomarker for the detection of AD." (PMID 37513692, 2023). "In contrast, in a mouse model of Alzheimer’s disease, a 2-fold increase in endogenous BDNF caused by the reduction of microRNA (miR)-206, a direct negative regulator of BDNF levels, alleviates the disease phenotype." (PMID 36476595, 2022). "Alzheimer’s disease is also marked by reductions in BDNF expression caused by decreased CREB-associated transcription of exon IV." (PMID 35418836, 2022). "Aging increases the risk of Alzheimer’s disease and neuroinflammation via microglial priming, resulting in the disbalance of BDNF/ProBDNF and/or TrkB/TrkB.T1, an impairment of synaptic plasticity, and a decline in cognitive function." (PMID 35887075, 2022). "Accordingly, indirect evidence supports targeting BDNF transmission to enhance PKC activation for the prevention of synaptic loss in Alzheimer’s disease." (PMID 35955546, 2022). "For instance, apathy has also been linked with other biomarkers associated with Alzheimer’s disease, including amyloid, tau, and brain-derived neurotrophic factor (BDNF)." (PMID 35742625, 2022). "For instance, reduced expression of BDNF and polymorphism -are closely associated with Alzheimer’s disease (AD) progression." (PMID 35668928, 2022). "Deficiencies in the BDNF/TrkB/Akt activity have been identified in several neurodegenerative diseases such as Alzheimer’s disease." (PMID 35186478, 2022). "Changes in BDNF expression leading to reduced function are associated with aging, exposure to chronic stress and neurodegenerative disease, such as Alzheimer’s disease." (PMID 34208002, 2021).
Alzheimer disease (continued). "Growing evidence suggest that decreases in BDNF content and defects in its signaling pathway via its receptor, TrkB, are associated with neurodegeneration and the progression of Alzheimer’s disease." (PMID 34017238, 2021). "Existing data support a possible effect of BDNF polymorphisms, mainly C270T and Val66Met on the risk of Alzheimer’s disease (AD)." (PMID 34621159, 2021). "BDNF is also implicated in various neuronal disorders such as Alzheimer’s disease, Huntington’s disease." (PMID 32041280, 2020). "Several reports suggest that a reduction in BDNF expression levels is a major factor underlying the emergence of diverse neurological and neurodegenerative disorders, such as Alzheimer’s disease." (PMID 32106593, 2020). "CREB activity and BDNF expression are remarkably suppressed in Alzheimer disease (AD) patients and AD animal models, and it is associated with cognitive decline." (PMID 32460803, 2020). "For example, a decrease in BDNF expression was correlated with neuronal loss in neurodegenerative diseases, including Parkinson’s disease or Alzheimer’s disease." (PMID 31849731, 2019). "Decreased levels of BDNF are associated with neurodegenerative diseases with neuronal loss, such as Parkinson’s disease, Alzheimer’s disease, multiple sclerosis and Huntington’s disease." (PMID 29930382, 2018). "Here we review the role and relevance of the BDNF Val66Met polymorphism in neurodegenerative diseases, with particular emphasis on glaucoma, multiple sclerosis (MS), Alzheimer’s disease (AD) and Parkinson’s disease (PD)." (PMID 29896439, 2018). "The C270T (rs56164415) polymorphism located in the non-coding region of BDNF was found to be associated with increased risk of late-onset Alzheimer’s disease (LOAD) and also linked with susceptibility to and the onset of MS." (PMID 29896439, 2018). "Several genetic studies have shown a significant association between schizophrenia, Alzheimer's disease, and Parkinson's disease and certain BDNF polymorphisms, specifically G196A (rs6265) and C270T (rs56164415)." (PMID 28539884, 2017). "Dysfunction of BDNF is associated with depression, schizophrenia, cerebral trauma and Alzheimer's disease (AD)." (PMID 28947961, 2017). "BDNF gene expression is critical for signaling during many forms of learning and memory and its misregulation is strongly implicated in Alzheimer′s disease and other learning disorders." (PMID 28208656, 2017). "Aberrant levels of BDNF have been implicated in a number of neurological diseases such as Alzheimer’s disease (AD), Parkinson’s disease (PD), Huntington’s disease (HD) and amyotrophic lateral sclerosis (ALS)." (PMID 28272318, 2017). "BDNF levels are lower in the brains of individuals with Alzheimer's disease (AD), suggesting a pathogenic involvement." (PMID 25954034, 2015). "RORα also potentially regulates transcription of brain-derived neurotrophic factor, which is associated with Alzheimer’s disease." (PMID 26383638, 2015). "Changes in BDNF levels have also been implicated in a variety of neuropsychiatric disorders, including Alzheimer’s disease, bipolar disorder, schizophrenia, and depression." (PMID 25601223, 2015). "An emerging body of data suggests that the early onset of Alzheimer’s disease (AD) is associated with decreased brain-derived neurotrophic factor (BDNF)." (PMID 25849905, 2015). "For example, genetic variation in encoding brain derived neurotrophic factor (BDNF) has been implicated in neuropsychiatric disorders such as Alzheimer's disease, affective disorders, schizophrenia, and substance dependence." (PMID 25018719, 2014).